IL11 (interleukin 11)
Diseases named in the same sentence as IL11 in open-access papers (continued):
Sharing a sentence is not in itself a finding about the gene and the disease.
myeloma (11 papers, 2008 to 2024). "In bone disease associated to multiple myeloma, the production of IL-11 is stimulated by hepatocyte growth factor (HGF)." (PMID 34201209, 2021). "Even if these results derived from in vitro studies, they underline that a cytokine network works to make IL-11 available with important effects on aberrant bone resorption, which characterizes multiple myeloma." (PMID 34201209, 2021). "In non-myeloma in vivo studies, treatment with IL-11 has reduced bone formation, but also has a described role in promoting osteoclastogenesis." (PMID 34501423, 2021). "IL-11 is frequently quoted as a known OIF in myeloma, but few research studies have focussed on its role." (PMID 34501423, 2021). "Apoptotic osteocytes are increased in patients with multiple myeloma; they produce high levels of IL-11, which can stimulate osteoclast formation, and they augment their expression of IL-11 after a bone lesion develops." (PMID 32640686, 2020). "We show here that syndecan-1 positive (CD138+) myeloma cells secrete nanovesicles that are taken up by osteoblast-like cells and increase the secretion of IL-11 in the recipient cells." (PMID 26082068, 2012). "Some investigators have concluded that the leukocytosis is in response to the myeloma because monoclonal B-cell clones in myeloma can produce cytokines which are able to activate stromal cells to produce IL-6, IL-7, and IL-11 to stimulate T lymphocytes to produce IL-3 and GM-CSF." (PMID 25143840, 2014). "In addition to being crucial for all stages of platelet generation and proliferation, a number of cytokines, including thrombopoietin (TPO), interleukin-6 (IL-6), interleukin-11 (IL-11), and interleukin-1b (IL-1b), are also involved in the pathology of myeloma." (PMID 38818376, 2024). "As TGF-β1 and IL-1 overload the impact of HGF on IL-11 production, it was postulated that HGF from myeloma cells induces MMBD via IL-11." (PMID 34163520, 2021). "Our previous study of inflammation in the context of myeloma and its asymptomatic stage (MGUS) revealed that except for four cytokines found to be significantly higher in myeloma (HGF, IL-11, RANTES, SDF-1α), the levels of 38 inflammation cytokines were similar in MGUS and in myeloma." (PMID 32872203, 2020). "An HGF/Met/IL-11/IL-6/gp130/STAT3 cascade was found to be activated in PV clonal erythroblasts; activation of a similar autocrine HGF/IL-11/IL-6 cascade has been described in multiple myeloma and in solid tumours." (PMID 25119536, 2014). "Myeloma cells adhere to the stromal cells and induce secretion of OAFs including interleukin (IL)-6, IL-1, tumor necrosis factor (TNF), IL-11, macrophage inflammatory protein-1α (MIP-1α), hepatocyte growth factor (HGF), parathyroid hormone-related peptide (PTHrP), and others." (PMID 18577267, 2008).
periodontitis (11 papers, 2012 to 2024). An acute or chronic inflammatory process that affects the tissues that surround and support the teeth. "Aydin and Dilsiz reported elevated levels of oncostatin M (OSM), leukemia inhibitory factor (LIF), and IL-11 in the saliva of patients with periodontitis and gingivitis, with levels decreasing following periodontal treatment." (PMID 39410587, 2024). "A cascade of inflammatory proteins and enzymes is directly involved in periodontitis’ osteoclastogenesis, including proinflammatory cytokines such as IL-1β, IL-6, IL-11, IL-17, and TNF-α (point 6)." (PMID 38792574, 2024). "The most important finding was that anti-inflammatory cytokines IL-2, IL-4, and IL-11 levels in GCF of aggressive periodontitis cases were lower compared to chronic periodontitis subjects." (PMID 34104811, 2021). "In patients with aggressive periodontitis, IL-11 was decreased in periodontal pockets, pointing at a shift of the inflammatory equilibrium towards a more pro-inflammatory state." (PMID 25197981, 2014). "Further investigations with larger populations are required to clarify the specific contribution of IL-17 to the pathogenesis of periodontitis and to determine the therapeutic benefit of IL-11 for resolution of inflammation in periodontal diseases." (PMID 23226926, 2012). "Concentrations of IL-11 were significantly higher in the affected gingiva than in healthy sites in samples taken from the biopsy specimens of patients with periodontitis, indicating a putative function of IL-11 in the gingival tissue during the initial phase of gingival inflammation." (PMID 37762876, 2023). "It was previously reported that IL-11 is underexpressed in periodontitis, while TNF-α is overexpressed, there is a reduction of VEGF in periodontal disease, and these are correlated with the resolution of periodontal inflammation and periodontal tissue healing." (PMID 36826852, 2023). "On the other hand, plasma levels of all the interleukins studied (IL-1β, IL-6, IL-11) were not significantly different between study groups (chronic periodontitis, generalized aggressive periodontitis, gingivitis, healthy subjects)." (PMID 25299619, 2014). "The levels of the pro-inflammatory cytokine IL-17 in gingival crevicular fluid (GCF) of aggressive periodontitis are higher than in GCF of chronic periodontitis patients, whereas the levels of IL-11, an anti-inflammatory mediator, were decreased in aggressive compared to chronic periodontitis." (PMID 25688342, 2014).
glioblastoma (10 papers, 2019 to 2025). The most malignant astrocytic tumor (WHO grade IV). "A recent study found that glioblastoma-associated microglia/macrophages secrete IL-11 into the tumour microenvironment, which promotes both tumourigenicity and resistance to temozolomide." (PMID 38248304, 2024). "Specifically, we explored a potential correlation between IL-11 and/or IL-11Rα expression in glioblastoma versus normal brain tissue and glioblastoma patient survival." (PMID 38248304, 2024). "To further elucidate the role of IL-11 signalling, we next utilised two primary glioblastoma cell lines that we had previously stably transfected with IL-11Rα." (PMID 38248304, 2024). "This study determined pro-tumourigenic role of IL-11 signalling in the glioblastoma setting using in vitro experimentation." (PMID 38248304, 2024). "Despite the growing evidence of the importance of IL-11 in these tumour types, the current knowledge regarding the literature on the role of IL-11 in glioblastoma progression is very limited." (PMID 38248304, 2024). "In the present study, we define a critical role for the IL-11/IL-11Rα signalling axis in glioblastoma proliferation, epithelial to mesenchymal transition, and invasion." (PMID 38248304, 2024). "Recently, we demonstrated the role of IL-11/IL-11Rα in promoting glioblastoma metabolic adaptation, leading to enhanced survival." (PMID 38248304, 2024). "Our current data also demonstrate a clear role in IL-11/IL-11Rα signalling promoting glioblastoma progression." (PMID 38248304, 2024). "Our current data mining of the TCGA demonstrated that IL-11 and the IL-11Rα expression negatively correlated with glioblastoma patient survival." (PMID 38248304, 2024). "Overall, our study identified that the IL-11/IL-11Rα pathway promotes glioblastoma cell proliferation, EMT, and invasion." (PMID 38248304, 2024). "We identified enhanced IL-11/IL-11Rα expression correlated with reduced overall survival in glioblastoma patients using TCGA datasets." (PMID 38248304, 2024). "Our previously published data have shown that IL-11 expression correlates with glioblastoma patient survival and that IL-11Rα expression promotes enhanced survival of glioblastoma cells." (PMID 38248304, 2024). "Our data establish a novel IL-11Rα signalling–glutaminolysis metabolism axis where IL-11/IL-11Rα can promote glutamine metabolism and subsequently enhance survival of glioblastoma cells in low-glucose microenvironments." (PMID 36834778, 2023). "Overall, our study identified that the IL-11/IL-11Rα pathway promotes glioblastoma cell survival and enhances cell migration and invasion in environments of glucose starvation via glutaminolysis." (PMID 36834778, 2023). "To further establish a model system to study the role of IL-11 signalling in glioblastoma cells, we stably transfected an IL-11Rα construct into the two cell lines (#20 and #28) with the lowest endogenous IL-11Rα expression." (PMID 36834778, 2023). "We identified enhanced IL-11/IL-11Rα expression correlated with reduced overall survival in glioblastoma patients." (PMID 36834778, 2023). "This was consistent with analysis of our glioblastoma patient tissue samples which revealed that IL-11 protein expression correlated with poor survival." (PMID 36834778, 2023). "Data were available for six cytokines in the IL-6 family in the TCGA database, with only IL-11 expression significantly correlated with poor glioblastoma patient survival." (PMID 36834778, 2023). "We propose that high IL-11/IL-11Rα expression leads to reduced apoptosis and subsequently greater glioblastoma progression and poorer patient survival rates potentially through enhanced glutaminolysis." (PMID 36834778, 2023). "In the present study, we define a critical role for the IL-11/IL-11Rα signalling axis in glioblastoma survival, proliferation and invasion when cells are starved of glucose." (PMID 36834778, 2023).
glioblastoma (continued). "We also found that the gene expression levels of IL-11 and IL-11Rα were increased in three of five primary glioblastoma cell lines and those patients in which the cell lines originated had decreased survival." (PMID 36834778, 2023). "Here we show a clear role of IL-11/IL-11Rα signalling in glioblastoma progression." (PMID 38248304, 2024). "Our findings here suggest that a therapeutic strategy that includes successful blocking of the IL-11 signaling pathway should result in reduced glioblastoma cell proliferation and invasion and thus could potentially improve patient outcomes." (PMID 38248304, 2024). "Together, our findings suggest that IL-11 may be a marker of glioblastoma tumour aggressiveness with prognostic value." (PMID 38248304, 2024). "Another study determined that IL-11 is secreted by glioblastoma cells." (PMID 38248304, 2024). "We found that IL-11 expression correlates with glioblastoma patient survival." (PMID 36834778, 2023). "The contribution of IL-11/IL-11Rα signalling to glioblastoma progression is under-explored." (PMID 36834778, 2023). "Interestingly, IL-11 expression was the only cytokine in the IL-6 family to correlate to glioblastoma patient outcomes." (PMID 36834778, 2023). "This novel mechanism of IL-11 signalling may partially explain why glioblastoma patients with higher levels of IL-11 have poorer overall survival." (PMID 36834778, 2023). "We also observed that the expression of IL-11 was significantly higher in glioblastoma compared to low-grade glioma samples, suggesting that IL-11 may play a role in the more aggressive glioma grades." (PMID 36834778, 2023). "Inhibition of GAM recruitment and IL-11 secretion by ablation or genetic inactivation of myeloid-specific phosphoinositide-3-kinase gamma isoform (PI3Kγ) reversed TMZ sensitivity in a murine glioblastoma model." (PMID 36013403, 2022). "Therefore, here we determined the role of IL-11 signalling in glioblastoma tumour progression." (PMID 38248304, 2024). "Both IL-11 and IL-11Rα gene expression were detected at significantly higher levels in glioblastoma patient tissue compared to normal brain tissue, while the protein expression of IL-11Rα was found to be higher in glioblastoma tissue compared to normal tissue using the Human Protein Atlas database." (PMID 38248304, 2024). "For example, elevated H3K9la promoted the transcription of interleukin-11, resulting in CD8+ T cell dysfunction in head and neck squamous cell carcinoma, as well as enhanced LUC7L2 transcription, conferring temozolomide resistance in glioblastoma." (PMID 40784455, 2025). "Both IL-11 and Il-11Rα gene expression significantly correlated with reduced overall survival in glioblastoma patients, despite neither of these genes having a large alteration rate." (PMID 38248304, 2024). "In cancer, IL-11 has been shown to have a similarly invasive role, although it has not yet been identified in the context of glioblastoma." (PMID 38248304, 2024). "However, the potential functional role of IL-11 in enhancing glioblastoma development and progression was not clearly determined." (PMID 38248304, 2024). "However, a definitive pro-proliferative role of IL-11/IL-11Rα signalling has not been identified in the glioblastoma setting." (PMID 38248304, 2024). "In addition, evaluating glioblastoma cells with varied IL-11 signaling (rather than our over or under-expressing systems used here) may also be important to conclusively identify Il-11 signaling as a critical pathway in glioblastoma pathogenesis." (PMID 38248304, 2024). "Moreover, glioblastoma associated microglia/macrophages up-regulate expression of the proinflammatory cytokine interleukin 11 (IL-11), resulting in activation of the STAT3-MYC pathway in GBM cells." (PMID 36555253, 2022).
melanoma (10 papers, 2011 to 2023). A malignant, usually aggressive tumor composed of atypical, neoplastic melanocytes. "Our results reveal that Wnt5a stimulates melanoma cells to secrete IL-6, IL-8, IL-11, MCP-1, IL-6sR, and sTNFRI." (PMID 31510045, 2019). "In particular, this transcriptional regulation involves the JAK/STAT pathway (JAK1, LIF, and IL11), which is a strong regulator of contractility in melanoma." (PMID 26526369, 2015). "Melanoma cells exposed to the high levels of exogenous TGFβ present in bone, upregulate osteolytic genes (including IL-11, PTHrP, and CTGF) which may aid more effective colonisation of this metastatic niche." (PMID 27835901, 2016). "Moreover, IL-11 displays anti-melanoma activity when used as molecular adjuvant in the therapeutic whole cell melanoma vaccine formulation." (PMID 22433466, 2012). "Six STAT3-inducing cytokines (IL-6, IL-11, MIF, PDGF-AA, OPN, and MCP-1), all expressed by melanoma, were tested for their ability to induce these alterations in microglia cells." (PMID 37296634, 2023). "It has been shown that YTHDF2 targets a plethora of mRNAs for degradation in cancers, such as, TNFR2, c-Myc and CEBPA in leukemia, EGFR, IL11, SERPINE2 and SOCS2 in liver cancer, and PD-1, CXCR4, and SOX10 in melanoma." (PMID 33658012, 2021). "Treg signature genes CXCR5, TNFRSF9, CCR7, STAT1, GBP4, and EOMES were significantly upregulated in the young cohort and were correlated with higher survival in melanoma, while ID3, IL-17A, IL-17F, RDH10 and IL-11 were significantly upregulated in the old cohort." (PMID 36135194, 2022).
osteoporosis (10 papers, 2012 to 2023). A condition of reduced bone mass, with decreased cortical thickness and a decrease in the number and size of the trabeculae of cancellous bone (but normal chemical composition), resulting in increased fracture incidence. "IL-11 is emerging as a novel target in the treatment of bone diseases such as osteoporosis and is also involved in weight loss and glucose intolerance." (PMID 37199584, 2023). "Therefore, further investigations are essential to clarify the mechanisms underlying IL-11’s effects on osteoporosis." (PMID 38352248, 2023). "Postmenopausal women who have osteoporosis show a significant increase in serum IL-11 levels, which were found to be positively correlated with the levels of bone resorption markers (NTX and DPyr)." (PMID 38352248, 2023). "We demonstrate that osteoblast/osteocyte-derived IL-11 controls both osteogenesis and systemic adiposity in response to mechanical loading, an important insight for our understanding of osteoporosis and metabolic syndromes." (PMID 36424386, 2022). "Thus, the therapeutic potential of IL-11 in osteoporosis and metabolic syndrome needs further verification." (PMID 37199584, 2023). "Moreover, IL-11 is produced by osteoblasts, which further implies a possible role of IL-11 signaling in osteoporosis." (PMID 31357561, 2019).
osteosarcoma (10 papers, 2011 to 2024). A usually aggressive malignant bone-forming mesenchymal neoplasm, predominantly affecting adolescents and young adults. "The in vitro legwork attested to this, revealing an impressive uptick in DOX internalization, apoptosis induction, and migration curtailment in IL-11R α-overexpressing 143B osteosarcoma cells when subjected to IL11-PDOX." (PMID 38140058, 2023). "When this insight was extrapolated to in vivo orthotopic and relapsed 143B osteosarcoma models, IL11-PDOX showcased a pronounced suppressive action against tumor proliferation and lung metastasis compared to standalone DOX treatment." (PMID 38140058, 2023). "Further consolidating its therapeutic validity, IL11-PDOX manifested commendable inhibitory prowess against patient-derived osteosarcoma xenografts." (PMID 38140058, 2023). "In some studies, polyP upregulated the cytokine interleukin 11 (IL-11) in human osteosarcoma SaOS-2 cells and PPK stimulated the secretion of a well-known inflammatory response mediator interleukin 8 (IL-8) in human embryonic intestine INT407 cells." (PMID 34991200, 2022). "It has been reported that HGF promotes RANKL expression via IL-11 secretion in the human osteosarcoma cell line, Saos-2." (PMID 33114380, 2020). "In brief, osteosarcoma cells produce soluble osteolytic factors such as interleukin-6 (IL-6), IL-11, tumor necrosis factor-α, or receptor activator of NF-κB ligand (RANKL) that activate osteoclastogenesis, leading to bone degradation." (PMID 29761075, 2018). "During the initial stages of osteosarcoma invasion, growth factors such as TGF-β are released from the degraded bone matrix and act on osteosarcoma cells, stimulating the release of PTHrP, interleukin-6 (IL-6) and interleukin-11 (IL-11)." (PMID 21559216, 2011). "IL-11 was also shown to increase proliferation, migration, and invasion in osteosarcoma." (PMID 38248304, 2024). "But what sets IL11-PDOX apart is its functionalization with IL-11R α-specific peptides, tailored to enhance chemotherapy specificity and efficacy against osteosarcoma." (PMID 38140058, 2023). "One hypothesis to explain this phenomenon is that blocking the TGF-β cascade in osteosarcoma cells inhibits the expression and secretion of the TGF-β target genes, such as RANKL and IL-11, which stimulate osteoclast activity." (PMID 29761075, 2018). "In addition, we recently demonstrated that blocking TGF-β signaling by overexpression of Smad7 in osteosarcoma cells inhibits the expression and release of osteolytic factors such as RANKL and IL-11 by tumor cells." (PMID 26015407, 2015). "Interestingly, however, in our preliminary experiments, neither the osteosarcoma-derived cell line MG63 nor the fetal osteoblastic cell line hFOB 1.19 showed an increased IL11 expression when exposed to ALBA or recombinant TGF-β." (PMID 38003371, 2023). "A response of osteocytes to IL-11 has not been reported previously, but IL-11 stimulates STAT3 phosphorylation in primary calvarial osteoblasts, and we have observed downregulation of sclerostin by IL-11 in an osteosarcoma-derived cell line (UMR106-01, Patricia W.M. Ho, unpublished data)." (PMID 32458800, 2020).